BDNF (brain derived neurotrophic factor)
Diseases named in the same sentence as BDNF in open-access papers (continued):
Sharing a sentence is not in itself a finding about the gene and the disease.
Cognitive impairment (continued). "The study found some evidence of associations between BDNF and/or inflammatory factors and different stressors and functional and cognitive impairment, but limitations prevented firm conclusions." (PMID 35740389, 2022). "Low levels of brain BDNF are suspected to be involved in the cognitive impairment associated with stress-related mood disorders." (PMID 35563524, 2022). "The Mir-10b-dependent decrease in BDNF expression is accompanied by significant cognitive impairment, causes neuronal dysfunction and death, including the case of Huntington’s disease." (PMID 36613744, 2022). "The influence of variants of BDNF in cognitive deficit has also been studied; one example is BDNF Val66Met, which is related to a worse cognitive function." (PMID 34576069, 2021). "It is well established that during aging, the BDNF level reduces, which is associated with cognitive impairment." (PMID 35096297, 2021). "Our findings are of great significance in understanding the role of BDNF polymorphisms in the different domains of cognitive deficits in SZ patients at different stages." (PMID 34625629, 2021). "The present study shows that the chronic restraint stress induces anxiety/depressive-like behaviors and results in cognitive deficits, causes an abnormal change in the intestinal microbiota, and reduces the levels of 5-HT, BDNF, and TrkB." (PMID 33603935, 2021). "For instance, BDNF Met66 polymorphism was recently associated with a higher risk of cognitive impairment in PD, bipolar disorder, and depression." (PMID 33477654, 2021). "Discussion: Our results preliminarily suggest a protective role of BDNF Val66Met polymorphism against cognitive impairment in MS patients, possibly related to a detrimental effect of increased BDNF concentration in a neuroinflammatory environment." (PMID 33815257, 2021). "This study aimed to examine the effect of BDNF polymorphisms on cognitive deficits in drug-naïve first-episode (DNFE) patients and chronic patients with SZ." (PMID 34625629, 2021). "The gut microbiota dysbiosis has been associated with decreased levels of BDNF in the hippocampus and cortex, leading to cognitive disorders." (PMID 33642976, 2021). "Disruption of BDNF through methylation and, ultimately, reduced gene expression, has been associated with schizophrenia, cognitive impairments and hyperactivity." (PMID 34836233, 2021). "We found that SAE induced cognitive impairment in mice and was associated with an increased expression of proBDNF and p75NTR and a decreased expression of BDNF and TrkB in the hippocampus." (PMID 34354558, 2021). "The intracerebroventricular administration of LPS causes cognitive impairment through the suppression of NF-κB-mediated expression of BDNF and phosphorylation of CREB." (PMID 34579150, 2021). "Knowing that patients with CAD are at higher risk of cognitive impairment, the mechanisms behind this weakened protective effect of BDNF on platelet-related cognitive deterioration is worthy of further investigation." (PMID 34557534, 2021). "Exposure to this microbe caused significant cognitive impairment, including decreased spontaneous alteration in the Y-maze task and decreased BDNF expression and BNDF+/NeuN+ cell counts in the hippocampus." (PMID 32669127, 2020). "The BDNF Met allele has also been implicated in cognitive deficits outside of memory, including reduced visuospatial function performance in individuals with schizophrenia and executive function performance in older adults." (PMID 32218234, 2020). "Future work is necessary to understand if reduced alpha power associated with the BDNF Val66Met polymorphism is also an early risk factor for cognitive impairment." (PMID 33087740, 2020). "Other studies have documented that carriers of at least one BDNF 66Met allele presented a higher prevalence of cognitive impairment in PD patients." (PMID 33269104, 2020).
Cognitive impairment (continued). "Low plasma BDNF levels have been found significantly associated with brain amyloid burden measured with Pittsburg Compound B in AD and mild cognitive impairment patients, supporting a pathogenic and a peripheral signature role of BDNF." (PMID 32655365, 2020). "The BDNF Val66Met has been suggested to impair activity dependent release of BDNF 12, play a role in BDNF/pro-BDNF secretion ratios 13, and is also associated with increased susceptibility to cognitive deficits and neuropsychiatric disorders 14,15." (PMID 33173426, 2020). "A meta‐analysis also displayed that reduced BDNF levels were significantly associated with cognitive impairment in processing speed, verbal learning, and working memory in schizophrenia patients." (PMID 33047489, 2020). "It has been shown that cognitive impairment is noticeable in neurodegenerative diseases, which is associated with a lower serum BDNF level as compared to healthy individuals." (PMID 32759658, 2020). "It has been reported that an abnormal truncation of TrkB mediated by calpain results in dysregulation of BDNF/TrkB signaling and is associated with cognitive impairments in several neurodegenerative disorders." (PMID 31948437, 2020). "Exercise-induced BDNF secretion is associated with the improvement of anxiety, depression, and cognitive impairment in humans." (PMID 32485872, 2020). "We preliminarily explored the relationships among BDNF gene polymorphisms, BDNF plasma levels, and cognitive impairment in Chinese PD patients." (PMID 33047489, 2020). "Given the association between obesity and cognitive impairment, it is especially important to evaluate BDNF isoforms in this population, and to evaluate the effects of strategies designed to minimize impairments on executive function from abdominal fat." (PMID 32778721, 2020). "Cognitive impairments in rodent models of HD are linked to the improper diffusion of AMPARs in dendritic spines of hippocampal neurons through the dysregulation of brain-derived neurotrophic factor (BDNF)-TrkB-CaMKII signaling." (PMID 33425919, 2020). "On the other hand, it has been reported that miR-30a-5p is a potential biomarker for PD, targeting and suppressing BDNF expression in the prefrontal cortex, and a lower BDNF level is associated with greater cognitive impairments in PD patients." (PMID 33029119, 2020). "Reduced levels of BDNF protein in specific regions of the brain has been associated with cognitive impairment." (PMID 32088835, 2020). "A recent meta-analysis reported an association between the BDNF Met allele and cognitive impairments in PD for 532 patients and 802 controls (p = 0.003)." (PMID 33584494, 2020). "It has been suggested that maternal iron deficiency is associated with offspring cognition impairment, decreased BDNF concentrations, low plasma acetate concentrations, and an altered microbiota." (PMID 32825437, 2020). "In the future, cognitive impairment caused by different doses and time of ketamine addiction patients can be measured with cognitive scale, and serum BDNF concentration can be measured at the same time." (PMID 33088278, 2020). "The results of experimental studies reveal also an association between the severity of cognitive impairment and BDNF concentration." (PMID 31701356, 2020). "Thereby, cognitive impairments after muscle regeneration were associated with an increase of brain BDNF level and a decrease of brain NGF level." (PMID 32066806, 2020). "This latter study estimated BDNF Met carriers with the APOE ε4 allele would have clinically significant cognitive impairment in 3 years, as compared to 10 years if the individual was an APOE ε4 carrier and BDNF Val homozygote." (PMID 32218234, 2020). "In the brain, exercise‐induced increase in hippocampal BDNF promotes neurogenesis and improves cognition, while conversely, BDNF deficiency contributes to cognitive impairment and neurodegenerative diseases." (PMID 31883222, 2019).
Cognitive impairment (continued). "Defects in the mechanism of conversion of pro-BDNF into BDNF or an altered balance of the two forms have been linked with cognitive impairment, psychiatric disorders, and anxiety-like behaviours." (PMID 31118969, 2019). "As well as lower BDNF levels in cerebrospinal fluid (CSF) from patients with Alzheimer’s disease, reduced CSF levels of BDNF are also associated with progression from mild cognitive impairment to Alzheimer’s disease." (PMID 31413298, 2019). "Central PPARγ stimulation induced the expression of BDNF and thus suggested a potential molecular signaling pathway, improving cognitive deficits associated with diabetes related to PPARγ." (PMID 31614739, 2019). "In conclusion, the BDNF gene rs6265 polymorphism plays important roles in cognitive impairment in Parkinson's disease, especially among Caucasian populations." (PMID 31365694, 2019). "With respect to the effects on behavior, most studies associate a reduction in BDNF with cognitive deficits." (PMID 30585393, 2019). "Nevertheless, more large-sample studies following the unified diagnostic criteria for cognitive impairment in PD are needed to further confirm the relationship between BDNF rs6265 and the pathogenesis of PD." (PMID 31365694, 2019). "Several studies have recently investigated the association between BDNF G196A (Val66Met), a single nucleotide polymorphism influencing cognitive processes, and cognitive impairment in Parkinson's disease (PD), but with contradictory findings." (PMID 31365694, 2019). "Nevertheless, investigating the relationship between BDNF genotype, memory, and neural mechanisms in BD alone can still be used to identify potential mechanisms underlying the heterogeneity in cognitive impairment across BD patients." (PMID 31866880, 2019). "The association between higher BDNF levels and cognitive impairment, mainly attention in smokers appears to be dependent on the BDNF Val66Met polymorphism." (PMID 30659208, 2019). "Recently, it was reported that low expression levels of BDNF are associated with cognitive deficits in patients with diabetes." (PMID 31165005, 2019). "Impaired BDNF signaling in the frontal and striatal regions during nicotine withdrawal was also associated with cognitive deficits." (PMID 31396113, 2019). "In conclusion, BDNF G196A (Val66Met) is confirmed to be a risk factor for cognitive impairment in PD." (PMID 31365694, 2019). "Depletion of microglia caused cognitive deficits and removal of microglial-derived brain derived neurotrophic factor recapitulated these effects, implicating microglial neurotrophic support in learning and memory." (PMID 30499006, 2019). "BDNF levels among the smokers who were Val allele carriers were correlated with the degree of cognitive impairments, especially attention, as well as with the carbon monoxide concentrations." (PMID 30659208, 2019). "One of such markers, lower serum level of BDNF has been shown to be associated with cognitive impairments in a sample of 59 cancer patients receiving chemotherapy for metastatic disease." (PMID 29864112, 2018). "This is also supported by a significantly lower level of BDNF in individuals with cognitive decline-associated disorders, such as AD and mild cognitive impairment." (PMID 29423073, 2018). "Low peripheral levels of BDNF is associated with lower cognitive test scores and mild cognitive impairment and frailty." (PMID 30096932, 2018). "Cognitive impairment in aging has been mainly associated with brain inflammation but also to a singular deficit of BDNF, an important neurotrophic factor participating in memory and learning." (PMID 30618722, 2018). "Decreasing or eliminating the expression of CREB or BDNF, due to stress or pharmaceutical or transgenic methods, causes emotional and cognitive impairment, such as in long-term memory consolidation and in spatial cognition in the Morris water maze." (PMID 29849577, 2018).
Cognitive impairment (continued). "In genetically susceptible mouse models, inducing cholinergic degeneration can exacerbate the production and/or accumulation of Aβ, and cause cognitive impairment, as well as resulting in reduced levels of BDNF, another feature of AD." (PMID 29520217, 2018). "The association between lower BDNF serum levels and cognitive impairment in T2DM is dependent on the BDNF Val66Met polymorphism." (PMID 29423073, 2018). "•A common human polymorphism in the gene that encodes brain derived neurotrophic factor (BDNF), Val66Met, is considered a marker of vulnerability for mental health issues and has been associated with cognitive impairment." (PMID 29909248, 2018). "The val66met SNP in the human BDNF gene is carried by approximately 30% of people worldwide and has been associated with cognitive deficits." (PMID 28751857, 2017). "The BDNF Met risk allele was found to be associated with both overall self-perceived cognitive impairment (p = 0.041) and self-perceived concentration deficit (p = 0.043)." (PMID 29258453, 2017). "A growing body of evidence suggests that severe stress can suppress BDNF signaling, impair synaptic activity and increase susceptibility to affective disorders, resulting in neuronal atrophy and cognitive impairment." (PMID 28806788, 2017). "EA or MA single- or multipoint stimulation at GV20 is widely studied and is associated with effects on BDNF signaling and cognitive impairment." (PMID 29234418, 2017). "Low serum BDNF levels have been correlated with Alzheimer’s disease and mild cognitive impairment, and high serum BDNF levels have been associated with better cognition in healthy older adults." (PMID 29258453, 2017). "The BDNF val66met polymorphism is carried by approximately 30% of people worldwide and has been associated with cognitive deficits." (PMID 28751857, 2017). "The BDNF pathway, in particular, has been implicated as a mediator between neuroinflammation and cognitive impairment." (PMID 28724382, 2017). "Decreased BDNF levels are associated with cognitive deficits in PD patients, and motor rehabilitation, besides improving PD symptoms, also increases BDNF levels, supporting our findings." (PMID 28713483, 2017). "The fact that BDNF Val66Met is associated with empathy also opens new research avenues for the study of psychopathologies involving social-cognitive deficits, such as autism or schizophrenia." (PMID 26901829, 2016). "Emerging evidence shows that abnormal BDNF/TrkB signaling is associated with the progression of AD and is involved in the production of Aβ, tau hyperphosphorylation and cognitive impairment." (PMID 26974541, 2016). "Consistent with our predictions, a higher genetic risk score significantly predicted a higher risk of having cognitive impairment (OR = 3.824, P = .013, and 95% C.I. = 1.333, 10.973) when controlling individual polymorphisms in BDNF, COMT, and APOE." (PMID 26366299, 2015). "Low peripheral BDNF is reported in first-episode psychosis (Buckley etal.2007) and is associated with cognitive impairment inchronically ill people with schizophrenia." (PMID 25162472, 2015). "After 8-month dietary supplementation, the MP diet (5000 ppm) significantly attenuated the cognitive impairment associated with anti-inflammation, increasing BDNF level and decreasing p-tau (phospho-tau S202) in older B6 mice." (PMID 25525451, 2014). "Single nucleotide polymorphism in BDNF val66met allele is implicated with increased risk for schizophrenia, and cognitive impairments and is mediated at least in part by activity-dependent trafficking and/or secretion of BDNF." (PMID 25414642, 2014). "Subtle cognitive deficits have been found in DAT KO mice that are associated with changes in brain derived neurotrophic factor in the prefrontal cortex." (PMID 25514162, 2014).
Cognitive impairment (continued). "Low BDNF is associated with verbal memory impairment and with cognitive impairment and dementia in women, while higher BDNF in the elderly is correlated with better performance on the mini mental status examination." (PMID 21886571, 2011). "BDNF Val66Met polymorphism is associated with cognitive impairment in Italian patients with Parkinson's disease." (PMID 21034472, 2010). "Recently, a BDNF regulatory locus has been discovered 850 kb upstream of the human and mouse BDNF genes that causes obesity, cognitive impairment and hyperactivity when disrupted." (PMID 19555478, 2009). "Alternative splicing of the TRKB gene, NTRK2, generates either the full-length receptor (TRKB-FL) or a truncated isoform (TRKB-T1) that inhibits BDNF signaling and has been implicated in neurodegenerative diseases, psychiatric disorders, and cognitive impairments." (PMID 41360765, 2025). "BDNF is a critical mediator of neuronal survival, differentiation, and synaptic plasticity, and its reduced expression has been associated with neurodegeneration and cognitive deficits in various models." (PMID 40283093, 2025). "Similarly, Chen reported that chronic administration of TSG prevented synaptic loss and cognitive impairment by increasing the expression of BDNF and CREB, maintaining synaptic plasticity in the hippocampus, and enhancing memory function." (PMID 41516109, 2025). "While low levels of BDNF may be linked to cognitive impairment, exercise-induced increases in circulating BDNF levels could contribute to improve neurocognition." (PMID 40537774, 2025). "This signalling pathway may mediate the effects of BDNF in LTP since Pyk2-deficient mice exhibited an impairment in LTP in CA1 synapses as well as a cognitive impairment in hippocampal-related tasks." (PMID 40890771, 2025). "Notably, BDNF is closely linked to cognitive disorders, with its signaling pathway associated with reduced apoptosis in hippocampal neurons and protection against hippocampal atrophy." (PMID 40726602, 2025). "Furthermore, VPA significantly affects acute levels of circulating brain-derived neurotrophic factor and corticospinal excitability, leading to a more substantial reduction in the risk of cognitive impairment." (PMID 41468384, 2025). "However, obesity and T2D often exhibit lower baseline levels of BDNF, which are linked to cognitive deficits and mood disorders." (PMID 41277875, 2025). "Based on this background, we hypothesized that alterations in NGF-β, BDNF, and vitamin D levels may be associated with symptom severity, cognitive deficits, and disease susceptibility." (PMID 40082848, 2025). "Among neurotrophins, brain-derived neurotrophic factor (BDNF) is most closely linked to OSA, with altered BDNF signaling associated with complications such as cardiovascular diseases and psychiatric disorders, including sleep disturbances, cognitive impairment, and depression." (PMID 39860451, 2025). "In parallel, AAV2-BDNF (NCT05040217) aims to evaluate whether BDNF, administered continuously via viral vector, can slow neuronal loss in patients with AD or mild cognitive impairment." (PMID 40722885, 2025). "Impairment of BDNF signaling is suggested to be a cause of cognitive impairment in this model." (PMID 40720390, 2025). "First, the polymorphism of BDNF, such as Val66Met, may be linked to elevated p-Tau and cognitive impairment." (PMID 40564462, 2025). "Neuroinflammatory and systemic inflammatory responses, particularly increases in pro-inflammatory cytokines (IL-6, IL-1β, TNF-α) and reductions in hippocampal BDNF, are consistently linked to breast cancer and chemotherapy-induced cognitive impairment in animal models." (PMID 41155372, 2025). "Proactive monitoring of inflammatory cytokines and neurotrophic markers such as BDNF could enable early identification of at-risk individuals and guide personalized interventions to mitigate long-term cognitive deficits." (PMID 40597835, 2025).